SMAD2 (SMAD family member 2)
Diseases named in the same sentence as SMAD2 in open-access papers (continued):
Sharing a sentence is not in itself a finding about the gene and the disease.
renal fibrosis (continued). "In conclusion, based on the in vivo and in vitro experiments, β-Mag retards the EMT and renal fibrosis by regulating the TGF-β/JNK/Smad2-mediated Snail/Vimentin axis." (PMID 39451219, 2024). "Juglone reduces matrix deposition, EMT, oxidative stress and attenuated renal fibrosis via the p-Smad2 and p-heat shock protein 27 (HSP27) pathways in Lewis rats with unilateral ureteral occlusion (UUO)." (PMID 38711994, 2024). "Phosphorylation of CREB after activation of PKA by cAMP can competitively bind CREB-binding protein with Smad complex, thus down-regulating p-Smad2 level, inhibiting proliferation of fibroblasts and collagen synthesis, and thus improving renal fibrosis." (PMID 38820434, 2024). "The expression of Smads is regulated by TGF-β1, with Smad2 and Smad3 being most closely related to renal fibrosis." (PMID 39712489, 2024). "In summary, β-Mag hampered renal fibrosis through the inhibition of the JNK/Smad2-mediated Snail/Vimentin axis." (PMID 39451219, 2024). "Multilineage ligand-receptor and cell-communication analysis showed that fibrosis-associated macrophages activated the TGF-β1/Smad2/3/YAP signal axis, which promotes mesangial fibrosis-like change and accelerates renal fibrosis niche." (PMID 38890734, 2024). "When β-Mag was administered, renal fibrosis was reduced, and the expression of both Smad2 and Snail was decreased in the β-Mag treatment." (PMID 39451219, 2024). "As the key driver of renal fibrosis, its down-stream Smad2 and Smad3 are activated in the fibrotic kidney of CKD patients and animal models." (PMID 38603722, 2024). "Collectively, the recruitment of MCs, activation of the TGF-β1/Smad2/3 pathway, and Ang II production drive renal oxidative stress, ultimately promoting the progression of renal fibrosis in hyperuricemic rats." (PMID 37446016, 2023). "E protein stimulates the release of HMGB1, which can promote activation of the TGF-β1/Smad2/3 signaling pathway and trigger the inflammatory response, both of which contribute to renal fibrosis." (PMID 37256223, 2023). "The protein expression levels of α-SMA, ED-1, TGF-β1, p-Smad2, and p-Smad3 were detected by western blot to analyze renal fibrosis and its regulatory mechanism." (PMID 36648018, 2023). "PTX also blocks TGF-β1 expression and Smad2/3 activation in renal fibrosis and decreases PAI-1/SERPINE1 expression in irradiated lung tissues and epithelial cells, thus preventing fibrosis." (PMID 37445768, 2023). "Although acetylation is reversible, the specific deacetylase responsible for SMAD2 deacetylation and its involvement in tubular epithelial cells and the process of renal fibrosis remain to be fully elucidated." (PMID 37777567, 2023). "Smad2 and Smad3 are almost similar (90%) but exhibit opposite effects, i.e., Smad2 is renal protective, whereas Smad3 is actively involved in renal fibrosis." (PMID 37559381, 2023). "The activation of SCF/c-kit leads to MC activation, promoting renal fibrosis through the TGF-β1/Smad2/3 pathway and aggravating renal oxidative stress injury." (PMID 37446016, 2023). "Evidence showed that it also increases renal fibrosis by activating TGF-B1 (transforming growth factor beta one)/SMAD2/3." (PMID 36833085, 2023). "The results show that the coadministration of SCG or VAL inhibited renal fibrosis in hyperuricemic rats by suppressing the TGF-β1/Smad2/3 pathway and decreasing MMP2 production to reduce ECM formation." (PMID 37446016, 2023). "Our findings suggested that the overexpression of the human‐specific CHRFAM7A gene can inhibit TGF‐β1‐induced EMT in HK‐2 cells and TGF‐β1/Smad2/3 signal axis, thus, reduce renal fibrosis that develops in response to obstructive nephropathy." (PMID 36479618, 2023). "The role of SMAD2 in TGF-β signaling is controversial in the setting of renal fibrosis as SMAD2 renal ablation aggravates fibrosis contrary to expectations." (PMID 37777567, 2023).
renal fibrosis (continued). "In summary, our experimental results show that the human‐specific CHRFAM7A gene can reduce renal fibrosis in mice with obstructive nephropathy by down‐regulating the TGF‐β1/Smad2/3 signalling pathway as well as inhibiting the release of inflammatory factors." (PMID 36479618, 2023). "The administration of the MCs membrane stabilizer, sodium cromoglycate (SCG), decreased the expression of SCF/c-kit, reduced the expression of α-SMA, MMP2, and inhibited the TGF-β1/Smad2/3 pathway, thereby alleviating renal fibrosis." (PMID 37446016, 2023). "For example, Shu’s study found that LDP attenuates diabetic nephropathy by inhibiting renal fibrosis through TGF-β/Smad2/3 pathway." (PMID 37198665, 2023). "TGF-β1 is often highly expressed in renal fibrosis, which promotes the occurrence and progression of renal failure by promoting downstream Smad2 and Smad3 and inhibiting the expression of Smad6 and Smad7." (PMID 38259279, 2023). "Collectively, our findings demonstrate that overexpression of the human‐specific CHRFAM7A gene can reduce UUO‐induced renal fibrosis by inhibiting TGF‐β1/Smad2/3 signalling pathway to reduce inflammatory reactions and EMT of renal tubular epithelial cells." (PMID 36479618, 2023). "Ang II incorporates in hypertension and high levels of blood pressure, mediates renal inflammation via NF-κB signaling activation, and improves renal fibrosis via TGF-β1/Smad2/3 pathway." (PMID 37184799, 2023). "Our investigations have revealed that SIRT2 suppresses renal fibrosis by inhibiting pro-fibrotic TGF-β signaling through the promotion of deacetylation of SMAD2 and SMAD3." (PMID 37777567, 2023). "Here, the authors show that neuraminidase 1 promotes renal fibrosis development by interacting with ALK5 to activate SMAD2/3." (PMID 36973294, 2023). "YAP1 inhibition by Verteporfin impairs TGF-β-induced Smad2/3 nuclear accumulation and transcriptional activity to attenuate renal fibrosis in response to mechanoregulators of organ stiffening." (PMID 35356283, 2022). "FGF21 prevents renal fibrosis by negatively regulating TGF-β/SMad2/3-mediated epithelial-to-mesenchymal transition in the diabetic mouse." (PMID 35369322, 2022). "An experimental study in a mouse model of unilateral ureteral obstruction showed that TGF- β induced up- regulation of miR-21 expression, which was mediated by Smad2 signal, thus promoting renal fibrosis." (PMID 35720359, 2022). "Currently, in preclinical studies, pirfenidone and fresolimumab are considered as a potential therapeutic way for renal fibrosis, which is the direct blockade of the TGFβ-Smad2/3 classical signaling pathway with antagonists or inhibitors." (PMID 36160854, 2022). "FGF21 can negatively regulate TGF-β1-induced Smad2/3 nuclear translocation, and reduce collagen precipitation and renal fibrosis." (PMID 34830222, 2021). "In this way, RvD1 attenuated renal fibrosis through the inhibition of Smad2 linker phosphorylation in the UUO model." (PMID 34769064, 2021). "It is possible to prevent OTA-induced EMT related renal fibrosis through regulating TGF-β/Smad2/3 and B-catenin/Wnt pathways." (PMID 34681895, 2021). "Blockade of downstream targets of the TGF-β/Smad signaling pathway inhibits both renal fibrosis and inflammation by blocking both the Smad2/3 and NF-κB signaling pathways in rat remnant kidney and UUO models." (PMID 34831283, 2021). "Few recent studies have reported that Smad3 silencing reduces the severity of renal fibrosis and that Smad2 promotes EMT by up-regulating CTGF and VEGF expressions in mice." (PMID 32515466, 2020). "Present results, therefore, support the notion that TGF‐β/Smad‐related proteins p‐Smad2 as well as p‐Smad3 are up‐regulated, whereas Smad7 expression decreased in renal fibrosis models compared with that in the controls." (PMID 32253812, 2020).
renal fibrosis (continued). "Another example of non-canonical transcription factors cooperating with SMADs are Hippo signaling effectors Yes-associated protein (YAP)/transcriptional co-activator with PDZ-binding motif (TAZ) cooperating with p-SMAD2/3 in driving the renal fibrosis." (PMID 33322749, 2020). "Overexpression of Smad2 attenuated TGF-β1-induced phosphorylated Smad3 and collagen expression, whereas deletion of Smad2 promoted renal fibrosis via substantially enhanced Smad3 signaling." (PMID 32266267, 2020). "HK-2 cells were stimulated by TGF-β, a critical mediator of renal fibrosis, resulting in significant increases in the phosphorylation of Smad2/3 and expression of Smad 4, which are downstream signals of TGF-β, along with increased expression levels of α-SMA." (PMID 32144368, 2020). "Recent studies have demonstrated the activation of Smad2/3 in TGF-β1 signaling-mediated renal fibrosis." (PMID 32714415, 2020). "Oleanolic acid reduced the expressions of TGF-β, TβRI, and TβRII and the phosphorylation of Smad2, suggesting oleanolic acid attenuated renal fibrosis through the TGF-β/Smad pathway." (PMID 32328123, 2020). "While Smad2 deletion in mouse tubular epithelial cells accelerated renal fibrosis by enhancing SMAD3 activation, conditional deletion of Smad4 in mouse tubular epithelial cells significantly reduced fibrosis without affecting SMAD3 activation." (PMID 33322749, 2020). "Both SMAD2 and 3 are upregulated in a variety of mouse models and in human tissues even at early ADPKD disease stages where they are associated with renal fibrosis and epithelial-to-mesenchymal transition (EMT) processes." (PMID 31919453, 2020). "We conclude that pharmacological manipulation of TRPM7 using NS8593 interferes with Smad2/3 phosphorylation in renal fibrosis." (PMID 32047249, 2020). "We previously showed Smad2 protects against renal fibrosis by limiting Smad3 signaling, but details on its role in acute phase are unclear." (PMID 31754396, 2019). "In the TGF-β/Smad pathway, Smad2 and Smad3 were known to accelerate renal fibrosis, whereas Smad 7 can inhibit TGF-β signal transduction to prevent fibrosis." (PMID 31687039, 2019). "Although Smad2 and Smad3 have more than 90% homology in amino acid sequence and interact physically, their functions differ in renal fibrosis." (PMID 31754396, 2019). "Elevated TGFβ1 and downstream Smad3 and Smad2 in the kidney activate profibrotic genes and mediate renal fibrosis." (PMID 31531112, 2019). "Once Smad7 is degraded through the ubiquitin proteasome degradation mechanism, Smad2/3 is activated, and renal fibrosis is enhanced." (PMID 30713574, 2019). "This is consistent with previous studies that have shown that Smad3 and Smad2 can counteract each other especially in renal fibrosis and inflammation." (PMID 29700311, 2018). "TGF-β1 have also induced elevation of Smad2 expressions that promoted renal fibrosis via insulin like growth factor binding protein-7 (IGFBP7)." (PMID 30496316, 2018). "In cystic epithelial cells of end-stage PKD, TGF-β1, and SMAD2/3 signaling was upregulated and associated with renal EMT and renal fibrosis." (PMID 28168444, 2017). "Despite having very high (90%) structural similarity, Smad2 and Smad3 differ in functionality and they play opposing roles in renal fibrosis." (PMID 27610006, 2016). "Although Smad2 and Smad3 share more than 90% similarity in their amino acid sequences, their functional roles in renal fibrosis are distinct." (PMID 25852569, 2015). "Extracellular Hmgb1 thus bound to TLR4, and by which, it activated MyD88-NFκB pathway to enhance IL-1β expression, which in turn promoted TGF-β/Smad2/3 and Pi3k/Akt signaling to exacerbate renal fibrosis." (PMID 26247732, 2015). "It has been observed that UUO induces an increase in Smad2 and Smad3 phosphorylation, and the contribution of TGF-β/Smad2/3 pathway in renal fibrosis have been extensively studied." (PMID 25313562, 2014).
renal fibrosis (continued). "The exogenous ALR (rhALR) inhibited Smad2 and Smad3 phosphorylation in UUO rats, which served a possible molecular mechanism underlying the antifibrotic capacity of ALR in renal fibrosis." (PMID 24844766, 2014). "Many studies have demonstrated that TGF-β promotes renal fibrosis through EMT by activation of Smad2/3 and was counteracted with BMP-7 by motivation of Smad1/5/8 to maintain the epithelial phenotype of TECs." (PMID 24350257, 2013). "Smad2 protects against TGF-beta/Smad3-mediated renal fibrosis." (PMID 40149644, 2025). "In the context of renal fibrosis, the AGEs/RAGE axis contributes to matrix accumulation, which is linked to increased TGF-β1 expression and activation of the canonical SMAD2/3 pathways, resulting in extracellular matrix deposition and glomerular basement membrane thickening." (PMID 40429870, 2025). "TB001 also inhibits the TGF-β1/Smad2/3/Twist pathway, further mitigating renal fibrosis." (PMID 40230860, 2025). "However, in accordance with a rat study, Smad2 has also been observed to defend against Smad3-dependent collagen accumulation and renal fibrosis both in vivo and in vitro." (PMID 39451219, 2024). "Consistent with previous studies that found that Smad2,Smad3,Smad4 and Smad7 might be involved in TGF-β1-mediated renal fibrosis, our study observed alterations in the phosphorylation activation of Smad2,Smad3,Smad4 and Smad7 in TGF-β1 treated HK-2 cells." (PMID 38195664, 2024). "The expression of genes that promote renal fibrosis (Smad2, Smad3, Smad4, Shh, Dll1) was downregulated, while the expression of genes that inhibit renal damage (Smurf1, Smurf2, Smad1, Smad5, Smad6, Smad7) was increased in the WT+miPEP31 group (PEP1/2) compared with the WT+ cPEP (SCR1/2) group." (PMID 38992718, 2024). "This indicates that inhibiting the TGF-β1/Smad2/3 pathway may be an important molecular mechanism by which MIX inhibits renal fibrosis in db/db mice." (PMID 39712489, 2024). "The important findings demonstrated that conditional deletion of Smad2 could significantly attenuate renal fibrosis." (PMID 38357745, 2024). "Additionally, our first study found that JNK/Smad2 activation was involved in TGF-β1-triggered EMT-mediated renal fibrosis in β-Mag-treated HK2 cells." (PMID 39451219, 2024). "TGF-β1 triggers the trans-differentiation of the intrinsic cells not only via the downstream Smad2/3-dependent pathways, but also stimulates the Smad2/3-independent signaling, including MAPKs, Wnt/β-catenin, RhoA, and PI3K/Akt, which are implicated in renal fibrosis." (PMID 38632264, 2024). "Similarly, a rat model of renal fibrosis induced by a high-salt diet showed a decrease in phosphorylated Smad2 and Smad3 following pirfenidone treatment, indicating that pirfenidone can mitigate fibrosis by altering the Smad signaling pathway." (PMID 39133399, 2024). "Literature demonstrated that the down-regulation of SMAD2/3 phosphorylation could prevent renal fibrosis." (PMID 37705751, 2023). "In response to high glucose, pro-inflammatory factor stimulation and oxidative stress, activated p38-MAPK targets and acts on TGF-β1, promoting the phosphorylation of Smad2/3 and increasing the expression of fibronectin, collagen I and IV (Col-I/IV), thereby playing a role in renal fibrosis." (PMID 36762989, 2023). "Studies have now demonstrated that TGF‐ β1 signalling through type I TGF‐β receptors leads to phosphorylation and nuclear translocation of Smad2 and Smad 3 that promotes renal fibrosis, while the overexpression of Smad7 prevents TGF‐ β1‐mediated renal fibrosis." (PMID 36479618, 2023). "In renal fibrosis, interestingly, although Smad2 shares a high degree of structural similarity to Smad3, overexpression of Smad2 attenuated TGF-β1-induced Smad3 phosphorylation and collagen I matrix, indicating that Smad2 works antagonistically to Smad3 in the progression of renal fibrosis." (PMID 38152335, 2023).
renal fibrosis (continued). "In conclusion, our study, for the first time, identified the chemical constituents in RSGB by UPLC-QTOF-MS/MS and demonstrate that the improvement of renal fibrosis by RSGB is related to the inhibition of Tgfβ1/Smad2/3 pathway, Wnt4/β-catenin pathway and NGFR/NF-κB pathway." (PMID 37198665, 2023). "TGFβ-Smad2/3 is a key pathway in the regulation of renal fibrosis." (PMID 36733505, 2023). "Our data imply that CHRFAM7A expression may alleviate renal fibrosis in UUO mice through inhibiting the TGF‐β1/Smad2/3 signalling pathway." (PMID 36479618, 2023). "Similarly, the TGF-β1/Smad2/3 signaling has been reported to be correlated with renal fibrosis and aberrant hyperplasia in diabetic nephropathy." (PMID 35264186, 2022). "Collectively, JP could alleviate the disease activity of MRL/lpr mice, improve renal function, and attenuate renal fibrosis, and its underlying mechanisms may be related to the inhibition of EMT and TGF-β1/Smad2/3 signaling pathway." (PMID 35591863, 2022). "Similarly, SMAD2 and SMAD7 are renoprotective in the course of renal fibrosis, wherein Smurf2 stimulates the degradation of SMAD2, resulting in weakened or repressed biological function." (PMID 35379779, 2022). "FGF21 could down-regulate TGF-β1 and induce nuclear translocation of Smad2/3 to reduce collagen precipitation and renal fibrosis." (PMID 34830222, 2021). "However, in the present study, we found that Smad7 protein levels in the UUO‐kidney of Gadd45β KO mice were up‐regulated, which subsequently reduce the phosphorylation of Smad2, resulting in less renal fibrosis." (PMID 32570293, 2020). "TGF-β-Smad2/3 signaling is recognized as a major pathway in progressive renal fibrosis." (PMID 33081058, 2020). "However, a recent finding that conditional deletion of Smad2 from TECs accelerates renal fibrosis reveals a protective role of Smad2 in renal fibrosis." (PMID 32258028, 2020). "In addition, FSP1-specific Smad2 knockout in renal tubular, endothelial, and interstitial cells is also reported to reduce renal fibrosis and epithelial-to-mesenchymal transition in murine streptozotocin (STZ)-induced diabetic nephropathy." (PMID 32258028, 2020). "The mechanisms by which mUC-MSC paracrine attenuates renal fibrosis involve the inhibition of MFT triggered by the TGF-β1/Smad2/3 signaling pathway and mesangial cell proliferation mediated by the PI3K/Akt and MAPK signal transduction pathways, and elevating MMP levels." (PMID 32455132, 2020). "Notch inhibition ameliorates renal fibrosis through inhibiting TGFβ/Smad2/3 signaling." (PMID 32724452, 2020). "Moreover, EPO has been shown to upregulate miR-200 expression and attenuate hypoxia-induced EMT in HK-2 cells as well as counteract TGF-β1-induced EMT by regulating TGF-β/Smad-2 signaling and inhibit renal fibrosis in UUO kidneys." (PMID 32993806, 2020). "Inhibition of the TGF-β1/Smad2/3 pathway alleviates kidney injury and renal fibrosis." (PMID 31531112, 2019). "Thus, rebalancing the TGF-β/Smad signaling pathway through the upregulation of Smad7 and the suppression of Smad2/3 activation are prospective treatment options for renal fibrosis." (PMID 30101622, 2018). "TGF-β induced Smad2/3 activation is the canonical pathway in renal fibrosis progression." (PMID 26872211, 2016). "The findings that disruption of Smad7 enhanced ANG II-induced renal injury by promoting TGF-β/Smad2/3-mediated renal fibrosis and NF-κB-driven renal inflammation added new information for a better understanding of the mechanism of Smad7 in negatively regulating ANG II-mediated kidney injury." (PMID 23301086, 2013). "Additionally, renal fibrosis is blunted by the TGF-β1/Smad2/3 pathway suppression." (PMID 39765782, 2024).